FOXI1 (forkhead box I1)
Description:
Transcriptional activator required for the development of normal hearing, sense of balance and kidney function. Required for the expression of SLC26A4/PDS, JAG1 and COCH in a subset of epithelial cells and the development of the endolymphatic system in the inner ear. Also required for the expression of SLC4A1/AE1, SLC4A9/AE4, ATP6V1B1 and the differentiation of intercalated cells in the epithelium of distal renal tubules (By similarity).
Synonyms: FREAC-6; HFH-3; FKHL10; FREAC6; FKH10; HFH3
Tractability: No criterion of Open Targets' tractability assessment is met for any kind of drug.
Gene: Protein-coding gene on chromosome 5 (170,105,897 to 170,109,734, forward strand). Ensembl gene ENSG00000168269.
Subcellular location: Nucleus
Subcellular location (Human Protein Atlas): Nucleoli; Vesicles
Gene Ontology:
Molecular function: DNA-binding transcription activator activity, RNA polymerase II-specific; DNA-binding transcription factor activity; protein binding; RNA polymerase II cis-regulatory region sequence-specific DNA binding; sequence-specific double-stranded DNA binding; DNA binding, bending; DNA-binding transcription factor activity, RNA polymerase II-specific; sequence-specific DNA binding; transcription cis-regulatory region binding
Biological process: positive regulation of transcription by RNA polymerase II; anatomical structure morphogenesis; cell differentiation; embryo development ending in birth or egg hatching; regulation of transcription by RNA polymerase II; positive regulation of DNA-templated transcription; regulation of DNA-templated transcription
Cellular component: nucleolus; chromatin; nucleus
Genetic constraint (gnomAD): Loss-of-function variants: 11 observed, 17.15 expected, observed/expected ratio (o/e) 0.64, 90% interval 0.4 to 1.06. The upper end of that interval is the gene's LOEUF score, 1.06, which puts it in group 4 of 6, group 1 being the genes least tolerant of losing a copy. Missense variants: 480 observed, 509.56 expected, observed/expected ratio (o/e) 0.94, 90% interval 0.87 to 1.02. Synonymous variants: 218 observed, 210.7 expected, observed/expected ratio (o/e) 1.03, 90% interval 0.93 to 1.16.
Gene-disease validity (ClinGen):
ClinGen rates the evidence that FOXI1 causes each of these diseases.
hearing loss disorder (autosomal recessive): Limited. A partial or complete loss of hearing in one or both ears.
enlarged vestibular aqueduct syndrome (autosomal recessive): Disputed.
Homologues: Orthologues: chimpanzee FOXI1 (98% identical), macaque FOXI1 (95% identical), dog FOXI1 (87% identical), rabbit FOXI1 (84% identical), mouse Foxi1 (84% identical), rat Foxi1 (83% identical), pig FOXI1 (83% identical), guinea pig FOXI1 (77% identical), tropical clawed frog foxi1 (70% identical), zebrafish foxp1b (20% identical), zebrafish foxp1a (20% identical). Paralogues in human: FOXF2 (22% identical), FOXP2 (20% identical), FOXP4 (19% identical).
Diseases named in the same sentence as FOXI1 in open-access papers:
FOXI1 is named in the same sentence as 44 diseases in open-access papers, as found by Europe PMC text mining. Sharing a sentence is not in itself a finding about the gene and the disease. The quoted sentences say what the papers report.
deafness (8 papers, 2008 to 2021). An inherited or acquired condition characterized by the complete loss of the ability to hear from one or both ears. "In a recent publication the first human data on mutations in FOXI1 was presented demonstrating an allelic contribution to human deafness in patients heterozygotic for SLC26A4 mutations." (PMID 19214237, 2009). "The FOXI1 gene encodes an important transcriptional factor, which is necessary for normal development of the inner ear, with mice that lack this gene developing deafness." (PMID 32375645, 2020). "Further analysis of these 11 families for deafness associated infertility genes such as FOXI1, CATSPER2 and STRC could possibly throw more light on the etiology of this phenotype." (PMID 29921236, 2018). "SLC26A4 and FOXI1 are also involved in determining syndromic forms of hearing loss with EVA, which are Pendred syndrome and distal renal tubular acidosis with deafness, respectively." (PMID 34562878, 2021). "It has been reported that EVA might also be caused by the heterozygote of SLC26A4 and FOXI1, or double gene inheritance of SLC26A4 and KCNJ10, which is the first example where double gene inheritance has been proven to be the cause of deafness in human beings." (PMID 34276761, 2021). "For the second question, Malin Hulander reported that the lack of pendrin expression led to deafness and expansion of the endolymphatic compartment in inner ears of Foxi1 null mutant mice." (PMID 19040761, 2008).
cystic fibrosis (7 papers, 2020 to 2024). Autosomal recessive disorder caused by pathogenic variants in the CFTR gene (cystic fibrosis transmembrane conductance regulator), which encodes a chloride and bicarbonate channel expressed in epithelial cells, and follow the diagnosis criteria. "In the lung, ionocytes express the ion channel CFTR, frequently mutated in individuals with cystic fibrosis and FOXI1 loss significantly decreases expression of CFTR in the mouse airway epithelium and leads to cystic fibrosis-like phenotypes." (PMID 39324331, 2024). "The level of MCC impairment in FOXI1-KO ferrets was also similar to CFTRG551D/G551D cystic fibrosis ferrets removed from treatment with a CFTR modulator (VX-770) that corrects the gating defect in the CFTRG551D channel." (PMID 37730992, 2023). "Like ionocytes in mouse airways and human LAE, the human SAE ionocytes highly expressed the transcription factors FOXI1 and ASCL3, V-ATPase-subunit genes (ATP6V1G3, ATP6V0B), and the Cl− ion channel CFTR, that when mutated, causes cystic fibrosis." (PMID 32727470, 2020). "Significantly downregulated genes in FOXI1-KO basal, secretory and ciliated cells included ATP12A, a proton pump involved in acidification of cystic fibrosis ASL16, and ATP1B1, an Na+/K+ ATPase." (PMID 37730992, 2023). "The airway epithelium contains ionocytes, a rare cell type with high expression of Forkhead Box I1 (FOXI1) transcription factor and Cystic Fibrosis Transmembrane conductance Regulator (CFTR), a chloride channel that is defective in cystic fibrosis." (PMID 32933106, 2020). "rno_circRNA_008646 sponges rno-miR-224 to upregulate the expression of forkhead box I1 (FOXI1), and circRNA_006061 activated p38/ATF3 pathway expression via sponging the rnomiR-128-3p, contributing to airway cystic fibrosis." (PMID 38601461, 2024). "Similar to human and pig cystic fibrosis cultures, FOXI1-KO and CFTR-KO ferret cultures failed to alkalinize the ASL following CFTR stimulation compared with wild-type cultures (P < 0.0001)." (PMID 37730992, 2023). "The pulmonary ionocytes express Forkhead box I1 (FoxI1), multiple subunits of the V-ATPase (Atp6v1c2 and Atp6v0d2), Cochlin, ASCL3, and the cystic fibrosis transmembrane conductance regulator (CFTR)." (PMID 35562719, 2022). "ALI cultures derived from cystic fibrosis ferret tracheal airway basal cells demonstrated a lack of CFTR-mediated currents and a significant increase in pulmonary ionocytes as assessed by the expression of transcription factors FOXI1 and ASCL3." (PMID 37730992, 2023).
Pendred syndrome (7 papers, 2013 to 2026). Pendred syndrome (PDS) is a clinically variable genetic disorder characterized by bilateral sensorineural hearing loss and euthyroid goiter. "Gain and loss of FOXI1 function are associated with human diseases, including Pendred syndrome, male infertility, renal acidosis, and cancers." (PMID 41490055, 2026). "Two other genes have been described to cause Pendred syndrome, accounting for less than 2% of affected individuals: FOXI1 encoding Forkhead box protein I1 and KCNJ10 encoding the adenosine triphosphate-sensitive potassium channel." (PMID 36529647, 2022). "Two genes, KCNJ10 and FOXI1, have been investigated for their role in the PDS disease spectrum and it has been proposed that digenic mutations in both SLC26A4 and either FOXI1 or KCNJ10 may cause Pendred syndrome." (PMID 23965030, 2013). "The present study investigates whether variants in KCNJ10 and FOXI1 in combination with heterozygosity for SLC26A4 mutations are likely to be associated with the disease phenotype seen in Pendred syndrome/EVA patients (who already have one mutation in the SLC26A4 gene)." (PMID 23965030, 2013). "It should be noted that autosomal recessive SNHL with EVA and/or Pendred syndrome also can be diagnosed with one pathogenic variant in SLC26A4 and one in either FOXI1 or KCNJ10." (PMID 36675424, 2023). "It was proposed that digenic inheritance of mutations in both FOXI1 and SLC26A4 were involved in the genetic basis of Pendred syndrome, as mutations in FOX1 were shown to reduce the transcription of SLC26A4." (PMID 23965030, 2013).
hearing loss (6 papers, 2013 to 2026). "Pathogenic variants in the SLC26A4, FOXI1, and KCNJ10 genes are associated with hearing loss (HL) and specific inner ear abnormalities (DFNB4)." (PMID 36499699, 2022). "FOXI1, NF2, MYO15A and CLIC5 genes, were among others associated with swimming impairment and hearing loss." (PMID 34829759, 2021). "Additionally, other genes such as the CEVA haplotype, FOXI1, KCNJ10, POU3F4, and possibly GJB2 are implicated in 50 %–60 % of cases of hearing loss and enlargement." (PMID 39481243, 2024). "Additional findings of double heterozygous mutations associated with hereditary hearing loss have been reported for KCNJ10 and SLC26A4 and for FOXI1 and SLC26A4, and some mutated genes may have a modifying effect." (PMID 24164807, 2013).
distal renal tubular acidosis (5 papers, 2010 to 2026). A kidney disorder of impaired net acid secretion by the distal tubule characterized by hyperchloremic metabolic acidosis. "Biallelic pathogenic variants in FOXI1 cause early-onset sensorineural deafness and distal renal tubular acidosis and FOXI1 knockout mice exhibit hearing loss, expansion of the inner ear compartments, and vestibular dysfunction." (PMID 40121402, 2025). "Overall, these findings have led to the hypothesis that mutations in the human FOXI1 gene might cause sensorineural deafness with distal renal tubular acidosis and male infertility." (PMID 20809947, 2010). "Foxi1 has also been recognised as a key factor necessary for correct patterning of distal nephron epithelium and adequate acid-base homeostasis in the kidney causing distal renal tubular acidosis in Foxi1-/- mice." (PMID 20809947, 2010). "Biallelic FOXI1 mutations lead to a complex syndrome called distal renal tubular acidosis with deafness (dRTA; OMIM #267300) in individuals who are negative for the known causative genes, which are SLC4A1, coding for a Cl−/HCO3− exchanger, and ATP6V0A4 and ATP6V1B1, coding for vacuolar proton pumps." (PMID 34562878, 2021). "Differentiation of ICs requires the winged helix transcription factor Foxi1, as Foxi1UB−/− mice develop distal renal tubular acidosis (dRTA) due to absence of ICs." (PMID 23704941, 2013).
gastric cancer (4 papers, 2017 to 2023). A primary or metastatic malignant neoplasm involving the stomach. "It has been reported that FOXI1 decreases gastric cancer cell proliferation through the posttranscriptional destabilization of WNT3A mRNA." (PMID 37011861, 2023). "miR-491-5p mediated by Foxi1 suppressed gastric cancer progression through inhibiting Wnt3α/β-catenin signaling." (PMID 35321519, 2022). "FOXI1-mediated miR-491-5p serves as a tumor repressor in gastric cancer via targeting Wnt3a/β-catenin pathway." (PMID 32808668, 2020).
chromophobe renal cell carcinoma (3 papers, 2022 to 2023). Chromophobe renal cell carcinoma is a rare subtype of renal cell carcinoma, originating from the intercalating cells of the collecting ducts and macroscopically manifesting as a well-circumscribed, highly lobulated, solid tumor that is usually diagnosed at an early stage. "Also, the role of the forkhead box 1 (FOXI1) transcription factor is investigated in the differential diagnosis of renal cancer, especially in the distinction between Renal Oncocytoma (RO) and chromophobe renal cell carcinoma (chRCC)." (PMID 36810541, 2023). "Interestingly, both FOXI1 and LINC01187 genes were recently reported to be involved in chromophobe renal cell carcinoma." (PMID 37056054, 2023).
Renal cyst (3 papers, 2022 to 2024). A fluid filled sac in the kidney. "Our published studies demonstrate that the knockout of Foxi1 in Tsc1 KO mice completely abrogates the development of renal cysts in these animals." (PMID 38731991, 2024). "The studies that are discussed in this review article demonstrate that in TSC renal cysts, A-IC cells that express both TSC1 and TSC2 constitute the cyst epithelium, and that FOXI1 plays a critical role in the process of cystogenesis." (PMID 38028758, 2023). "However, unlike the Tsc1/Foxi1 dKO mice, the Tsc1/Car2 dKO animals develop severe renal cystic disease as they age." (PMID 38731991, 2024).
asthma (2 papers, 2020 to 2025). "We found that a number of TFs were encompassed by BEC-SEs including TP63, a well-defined marker of basal cells, and TP73, a key player in mucociliary development and observed enrichment for FOXI1 sites in asthma DERs, a TF shown to characterize the recently identified ionocytes." (PMID 33362848, 2020). "Expression of known ionocyte markers FOXI1, ASCL3, PDE1C, TFCP2L1 and CFTR in single cells was lost in hBECs from patients with neutrophilic asthma (and reduced in paucigranulocytic asthma) compared to healthy donors or eosinophilic asthma." (PMID 39358991, 2025).
breast carcinoma (2 papers, 2022 to 2023). "FOXI1 is a transcription factor related to cell growth and differentiation and it has been associated with metastasis in breast cancer." (PMID 35736153, 2022).
cyst (2 papers, 2023 to 2024). A sac-like closed membranous structure that may be empty or contain fluid or amorphous material. "In these studies, we contrasted the ontogeny of cyst burden in Tsc1/Car2 dKO mice vs. Tsc1/Foxi1 dKO mice." (PMID 38731991, 2024). "Inactivation of carbonic anhydrase 2 (Car2) significantly reduced, whereas, deletion of Foxi1 completely abrogated the cyst burden in Tsc1 KO mice." (PMID 38731991, 2024). "The deletion of Foxi1, a protein that is vital to H+-ATPase expression and IC cell viability, completely inhibited mTORC1 activation and abrogated the cyst burden in 47-day-old Tsc1/Foxi1 dKO mice." (PMID 38731991, 2024). "The magnitude of cyst burden in Tsc1/Car2 dKO mice correlated with the expression levels of Foxi1 and was proportional to mTORC1 activation." (PMID 38731991, 2024). "Deletion of FOXI1, which is vital to H+-ATPase expression and IC cell development, completely inhibited mTOR activation and abrogated the cyst burden in Tsc1 KO mice." (PMID 38028758, 2023). "Deletion of FOXI1, which is vital to H+-ATPase expression and intercalated (IC) cell viability, completely inhibited mTORC1 activation and abrogated the cyst burden in the kidneys of Tsc1 KO mice." (PMID 38028758, 2023). "In contrast, the Tsc1/Foxi1 dKO mice displayed a complete absence of cyst formation at both 47 and 110 days of age." (PMID 38731991, 2024).
Infertility (2 papers, 2018 to 2024). "Fifteen males with both hearing loss and infertility from southern India after exclusion for the DIS contiguous gene deletion and the FOXI1 gene mutations are subjected to exome sequencing." (PMID 38884051, 2024).
male infertility (2 papers, 2013 to 2026). The inability of the male to effect fertilization of an ovum after a specified period of unprotected intercourse. "Mice lacking FOXI1 are deaf, have inner ear malformations (EVA and cochlear dysplasia) as well as renal tubular acidosis and male infertility." (PMID 23965030, 2013).
oncocytic neoplasm (2 papers, 2023 to 2024). A usually benign neoplasm composed of large cells with abundant eosinophilic granular cytoplasm. "However, this hypothetical relationship might not always be true because oncocytic neoplasms other than WTs in our study did not express FOXI1." (PMID 38358561, 2024).
oncocytomas (2 papers, 2023 to 2024). "Next, we examined FOXI1 and POU2F3 expression in common benign salivary gland tumors: WTs, PAs, basal cell adenomas, and oncocytomas." (PMID 38358561, 2024). "FOXI1-IHC showed that while all the WTs (10/10) and most of the PAs (9/10) contained FOXI1-positive cells, these cells were never observed in basal cell adenomas and oncocytomas, except for one basal cell adenoma that had a few FOXI1-positive cells." (PMID 38358561, 2024). "Importantly, sporadic ChRCCs and sporadic oncocytomas were further clustered into two distinct clusters, and differentially expressed genes (DEGs) analysis identified L1CAM, FOXI1 and its downstream gene, ATP6V0D2 as molecular markers for these distinct clusters (Group1 and 2)." (PMID 37182269, 2023).
Renal Oncocytoma (2 papers, 2023). "Research has shown that FOXI1 is a potential biomarker of IC-related renal tumours, such as ChRCC and renal oncocytoma." (PMID 36816543, 2023).
kidney cancer (1 paper, 2022). Primary or metastatic malignant neoplasm involving the kidney. "Birt-Hogg-Dubé (BHD)-associated kidney cancer exhibited transcriptomic intratumor heterogeneity (tITH) with increased characteristics of intercalated cells of the collecting duct and upregulation of FOXI1-driven genes, a critical transcription factor for collecting duct differentiation." (PMID 35874919, 2022). "Notably, in this study we observed increased expression of FOXI1 in BHD-associated kidney cancers." (PMID 35874919, 2022).
Kidney Cyst (1 paper, 2024). Abnormal fluid filled sac within the kidney, either acquired or congenital. "In this present study, we sought to examine the ontogeny of kidney cysts in Tsc1/Car2 dKO and Tsc1/Foxi1 dKO mice." (PMID 38731991, 2024). "We conclude that Car2 inactivation temporarily decreases the kidney cyst burden in Tsc1 KO mice but the cysts increase with advancing age, along with enhanced Foxi1 expression." (PMID 38731991, 2024). "In this present study, we examined the impact of aging on the kidney cyst burden in Tsc1/Car2 dKO mice and included age-matched Tsc1/Foxi1 dKO mice." (PMID 38731991, 2024). "This is in stark contrast to Tsc1/Foxi1 dKO mice, which showed a remarkable absence of kidney cysts at both 47 and 110 days of age." (PMID 38731991, 2024).
lung carcinoma (1 paper, 2025). "Validation at the single-cell level indicated that the FOXI1, FOXB1, and KCNA7 genes were linked to lung cancer progression." (PMID 40568194, 2025). "In lung cancer, only the clustered cell-like subpopulation significantly expresses FOXI1, which serves as a major regulator of ionocytes and a primary source of CFTR activity." (PMID 40568194, 2025). "Our findings identify an important link to lung cancer development and highlight KCNA7, FOXI1, and FOXB1 as marker genes for CXCL1 cancer subgroups relevant to clinical prognosis." (PMID 40568194, 2025). "Following transcriptomic and single-cell histological analyses, we established that the highly expressed transcription factors FOXI1, FOXB1, and KCNA7 promote lung cancer development and are primarily involved in cellular processes including proliferation, migration, and invasion." (PMID 40568194, 2025).
nasal polyps (1 paper, 2023). "In the self-paired comparison of the number of cells co-expressed by CFTR and FOXI1 in CRSwNP patients, it was found that the ionocytes that did not express CFTR in the nasal polyps were more common than those in the mucosa." (PMID 36662267, 2023).
salivary duct carcinoma (1 paper, 2024). An aggressive, high grade adenocarcinoma that arises from the salivary glands. "None of the cases of the five most common malignant salivary gland neoplasms, including mucoepidermoid, adenoid cystic, acinic cell, and salivary duct carcinomas, and polymorphous adenocarcinomas, contained FOXI1-positive cells." (PMID 38358561, 2024).